RUNX2 (RUNX family transcription factor 2)
Description:
Transcription factor involved in osteoblastic differentiation and skeletal morphogenesis. Essential for the maturation of osteoblasts and both intramembranous and endochondral ossification. CBF binds to the core site, 5'-PYGPYGGT-3', of a number of enhancers and promoters, including murine leukemia virus, polyomavirus enhancer, T-cell receptor enhancers, osteocalcin, osteopontin, bone sialoprotein, alpha 1(I) collagen, LCK, IL-3 and GM-CSF promoters. In osteoblasts, supports transcription activation: synergizes with SPEN/MINT to enhance FGFR2-mediated activation of the osteocalcin FGF-responsive element (OCFRE) (By similarity). Inhibits KAT6B-dependent transcriptional activation.
Synonyms: CBF-alpha-1; OSF-2; AML3; CBFA1; OSF2; PEBP2A1; PEBP2aA1; CCD; CCD1; CLCD; PEA2aA; PEBP2aA
Tractability: Small molecule: a structure with a bound ligand is known. PROTAC: UniProt records ubiquitination sites on it; ubiquitination databases record sites on it.
Gene: Protein-coding gene on chromosome 6 (45,328,157 to 45,664,349, forward strand). Ensembl gene ENSG00000124813.
Subcellular location: Nucleus; Cytoplasm
Subcellular location (Human Protein Atlas): Nucleoplasm
Pathways (Reactome):
Gene expression (Transcription): RUNX1 regulates transcription of genes involved in differentiation of myeloid cells; RUNX2 regulates bone development; RUNX2 regulates chondrocyte maturation; RUNX2 regulates genes involved in cell migration; RUNX2 regulates genes involved in differentiation of myeloid cells; RUNX2 regulates osteoblast differentiation; Regulation of RUNX2 expression and activity; Transcriptional regulation by RUNX2; YAP1- and WWTR1 (TAZ)-stimulated gene expression
Gene Ontology:
Molecular function: DNA-binding transcription activator activity; protein binding; sequence-specific double-stranded DNA binding; DNA-binding transcription factor activity; DNA-binding transcription factor activity, RNA polymerase II-specific; RNA polymerase II cis-regulatory region sequence-specific DNA binding; ATP binding; DNA binding
Biological process: negative regulation of DNA-templated transcription; osteoblast differentiation; positive regulation of DNA-templated transcription; positive regulation of osteoblast differentiation; positive regulation of transcription by RNA polymerase II; regulation of transcription by RNA polymerase II; SMAD protein signal transduction; BMP signaling pathway; chondrocyte differentiation; hemopoiesis; neuron differentiation; ossification; regulation of cell differentiation; cell surface receptor protein serine/threonine kinase signaling pathway; regulation of DNA-templated transcription
Cellular component: core-binding factor complex; nucleoplasm; nucleus; chromatin; cytoplasm; cytosol
Genetic constraint (gnomAD): Loss-of-function variants: 10 observed, 48.17 expected, observed/expected ratio (o/e) 0.21, 90% interval 0.13 to 0.35. The upper end of that interval is the gene's LOEUF score, 0.35, which puts it in group 1 of 6, group 1 being the genes least tolerant of losing a copy. Missense variants: 560 observed, 688.66 expected, observed/expected ratio (o/e) 0.81, 90% interval 0.76 to 0.87. Synonymous variants: 271 observed, 276.76 expected, observed/expected ratio (o/e) 0.98, 90% interval 0.89 to 1.08.
Homologues: Orthologues: mouse Runx2 (93% identical), rat Runx2 (93% identical), chimpanzee RUNX2 (90% identical), guinea pig RUNX2 (89% identical), tropical clawed frog runx2 (80% identical), zebrafish runx2a (74% identical), macaque RUNX2 (66% identical), pig RUNX2 (66% identical), rabbit RUNX2 (65% identical), dog RUNX2 (64% identical), Drosophila melanogaster run (27% identical), Caenorhabditis elegans rnt-1 (23% identical). Paralogues in human: RUNX1 (59% identical), RUNX3 (52% identical).
Diseases named in the same sentence as RUNX2 in open-access papers:
RUNX2 is named in the same sentence as 378 diseases in open-access papers, as found by Europe PMC text mining. Sharing a sentence is not in itself a finding about the gene and the disease. The quoted sentences say what the papers report.
breast carcinoma (205 papers, 2007 to 2026). "RUNX2 is a transcription factor involved in skeletal development, and while its overexpression is associated with elevated metastatic potential in breast cancer, its implications for low-grade gliomagenesis are unclear." (PMID 40307935, 2025). "Runx2 expression is reduced during late pregnancy, suggesting that it is necessary for full alveolar development in the mammary gland; moreover, loss of Runx2 expression increases mammary tumor survival." (PMID 38059614, 2024). "An immunohistochemistry-based study of breast cancer tissue samples obtained from 75 patients showed that a high RUNX2 level was significantly associated with poor prognosis, Ki-67 expression, and lymphatic metastasis." (PMID 37108164, 2023). "High expression of RUNX2 has been particularly associated with invasive, ER-negative cell lines resembling the basal subtype of breast cancer, such as MDA-MB-231, HCC38 and MDA-MB-157." (PMID 36831308, 2023). "This overexpression was observed mainly in the cytoplasm and was associated with the interaction between RUNX2 and α-Tubulin thus promoting microtubule stability in breast cancer cells." (PMID 37754231, 2023). "As a master regulator of osteoblasts and bone development, increased expression of RUNX2 has been implicated in breast cancer metastasis to bone." (PMID 36831308, 2023). "RUNX2, a gene most associated with cartilage production, has been linked to pancreatic cancer and to breast cancer progression through modulation of MicroRNAs and the metastasis-associated 1 (MTA1)/NuRD complex." (PMID 37895248, 2023). "Osteosarcoma, osteoarthritis, prostatic carcinoma, breast cancer, and gastric cancer have all been linked to RUNX2, which also plays a role in the differentiation and maturation of osteoblasts and chondrocytes." (PMID 37370857, 2023). "RUNX3 was part of a poor prognostic stromal gene signature in breast cancer patients, and very recently, RUNX1 (and also RUNX2) was identified through an epigenetic analysis of murine mammary tumors to be highly upregulated in cancer-associated fibroblasts." (PMID 36831308, 2023). "In agreement with a suspected pro-oncogenic role, loss of Runx2 slowed tumor growth in a mammary tumor model." (PMID 36831308, 2023). "In breast cancer, high expression of RUNX2 is associated with lower survival and is positively correlated with the risk of bone metastasis." (PMID 35805994, 2022). "Recent studies have shown that RUNX2 is overexpressed in several tumors and is associated with malignant progression and poor outcomes, such as osteosarcoma, prostate cancer, and breast cancer." (PMID 35534547, 2022). "We found that the loss of Runx2 increases the sensitivity of breast cancer cells to MT-targeting agents." (PMID 35884497, 2022). "Investigation of the association between RUNX2 expression and breast cancer patient prognosis also revealed that patients had a worse outcome as RUNX2 elevated." (PMID 35110544, 2022). "State-of-the-art renewal has indicated the involvement of RUNX-associated transcription factor 2 (RUNX2) in tumorigenesis and cancer progression, yet the detailed information during breast cancer is largely obscure." (PMID 36483054, 2022). "Through analysis of the TIMER database, we found that RUNX1 had highly frequent mutations in breast cancer, while RUNX2 and RUNX3 had a lower frequency of mutation rate." (PMID 34485309, 2021). "The intracellular domain of CD44 (CD44-ICD) has been implicated as a co-transcription factor for RUNX2 in the regulation of expression of MMP-9 in breast carcinoma cells." (PMID 31331331, 2019). "Previous studies showed that bcl-2 expression was inhibited by WWOX in breast cancer and bladder cancer, and that RUNX2 expression is up-regulated in WWOX-deficient mice." (PMID 28977834, 2017). "Expression and function of RUNX2 have been implicated in various human cancers, especially in breast cancer." (PMID 28978036, 2017).
breast carcinoma (continued). "For example, RUNX2 has been shown to be associated with the progression of prostate cancer, and tightly linked to bone metastasis of breast cancer cells." (PMID 27713122, 2016). "MMP-9 and MMP-13 are under the direct control of RUNX2 in a number of cell types, including breast cancer cells, and this was associated with invasive behavior of cancer cells." (PMID 26404249, 2015). "In breast cancer cells, high nuclear level of RUNX2 correlates with HER2 cellular status and this is associated with poor prognosis, although the worst outcome is linked with high RUNX2 and HER2-negative cases." (PMID 26404249, 2015). "Cells from bone metastatic breast cancer expressed exceptionally high level of RUNX2 and that was associated with a high tendency of cancer cells to metastase to bone." (PMID 26404249, 2015). "Numerous factors have been implicated in the progression of breast cancer metastasis, and among these is RUNX2, a bone-lineage transcription factor that promotes the invasive phenotype of MDA-MB-231 cells." (PMID 25120384, 2014). "High RUNX2 expression is limited to a subpopulation of breast cancer: it significantly associates with triple-negative (ER/PR/HER2-negative) disease and correlates with poorer patient survival." (PMID 24626992, 2014). "It has been shown that RUNX2 plays an important role in cell migration and invasion in breast cancer and higher expression is associated with poor outcome." (PMID 25266482, 2014). "A de-regulated serine/threonine kinase Akt signaling pathway is implicated in mammary carcinogenesis and cell survival; however, the mechanisms underlying Runx2 role in survival of invasive breast cancer cells are still unclear." (PMID 24479521, 2014). "This study investigated the association between RUNX2 and miR-10a/miR-10b and the risk of breast cancer relapse." (PMID 25266482, 2014). "Assessment of clinicopathological characteristics showed that RUNX2-high tumours significantly associated with ER-negative (P<0.005) and PR-negative (P<0.002) status, and with rare breast cancer types (P<0.05)." (PMID 24626992, 2014). "This correlation is restricted to Stage II because loss of the estrogen receptor and gain of RUNX2 function is typical in highly aggressive breast cancer cells." (PMID 21029421, 2010). "Our previous studies have shown that RUNX2 expression is positively linked to estrogen receptor status in tissue biopsies of Stage II breast cancer patients." (PMID 21029421, 2010). "Similarly, several studies have shown that RUNX2 is also closely associated with the occurrence and development of tumors, such as breast cancer, colorectal cancer, thyroid cancer, and pancreatic cancer." (PMID 38430423, 2024). "Moreover, elevated RUNX2 expression in breast cancer has been linked to enhanced tumor stem cell characteristics, thereby facilitating breast cancer cell metastasis." (PMID 38430423, 2024). "In addition, Runt-related transcription factor 2 (Runx2) dysregulation is associated with bone metastasis by autophagy and Runx2 is associated with migration in breast cancer cells." (PMID 36831154, 2023). "Aberrant expression of Runx2 has been linked with the progression of breast cancer and development of bone metastasis through the transcriptional upregulation of genes including VEGF, MMP-2, 9, 13, and IL-6 among others, which serve to promote tumor cell migration and invasion." (PMID 35884497, 2022). "Interestingly, it was reported that through its RUNX2 targeting capabilities, miR-203 was able to impair the progression of breast cancer as well as reduce its bone-associated metastases." (PMID 32230926, 2020). "Several studies showed the association of RUNX2 with the progression of prostate and breast cancer." (PMID 31331331, 2019). "Alcohol-increased Runx2 expression may play a crucial role in alcohol-associated breast cancer development." (PMID 31781337, 2019).
breast carcinoma (continued). "Also, we propose that low level of ANCR probably is associated with high level of RUNX2 in breast cancer tissues and breast cancer cell lines." (PMID 28978036, 2017). "Some studies also suggest that other breast cancer-related factors may be involved in the association between RUNX2 and estrogen signaling." (PMID 26404249, 2015). "Our results identified a novel mechanism of Runx2 regulatory crosstalk in Akt signaling that could have important consequences in targeting invasive breast cancer-associated cell survival." (PMID 24479521, 2014). "The work presented here, which shows that RUNX2 stimulates cell motility of breast adenocarcinoma cells, corroborates the concept that RUNX2 represents a prognostic marker for breast cancer progression that is mechanistically linked to the metastatic potential of the cells in which it is expressed." (PMID 21029421, 2010). "We also investigated whether the aberrant expression of RUNX2 is linked to phenotypic parameters that could provide a selective advantage to cells during breast cancer progression." (PMID 21029421, 2010). "Interestingly, the association of SMAD2/3 with RUNX2 has been reported previously in B-lymphocytes and human breast cancer cells." (PMID 19563662, 2009). "However, it is increased expression of RUNX2 that is generally associated with breast cancer transcriptomic datasets in both ER positive and ER negative subtypes, and accordingly, RUNX2 has been shown to adopt a pro-oncogenic role in breast cancer cells." (PMID 36831308, 2023). "Herein, we took advantage of breast cancer cell lines and in vivo tumorigenicity test as well as multifaceted phenotypic analyses (e.g., RNA-sequencing, ChIP and qRT-PCR assay) to verify the pathogenic mechanism of RUNX2 in triple negative breast cancer aggressiveness and chemoresistance." (PMID 36483054, 2022). "In breast cancer cells, Runx2 facilitates EMT by repressing E-cadherin, upregulating vimentin, and enhancing cellular invasiveness." (PMID 41596432, 2026). "In vitro experiments was carried out using MDA-MB-231 breast cancer cells to evaluate the regulatory effects of metformin on RUNX2 and mTORC2 signaling." (PMID 42038368, 2026). "Studies have shown that RUNX2 drives the progression and bone metastasis of breast cancer by forming the NuRD (MTA1)/CRL4B complex, which represses the transcription of genes critical for cell growth, EMT, and invasion." (PMID 40287769, 2025). "A study found that the transcription factor RUNX2 promotes drug resistance in triple-negative breast cancer through the TGF-β pathway by regulating breast cancer stem cells." (PMID 40413536, 2025). "miR-153 directly inhibits Runx2, thereby suppressing breast cancer cell proliferation, migration, and invasion, establishing the miR-153/Runx2 regulatory axis as a potential therapeutic target." (PMID 41230330, 2025). "Previous research has shown that CADD522 inhibits growth in breast cancer cells and improves outcomes in a xenograft mouse model of bone cancer by targeting Runx2." (PMID 41382107, 2025). "Runx2, abnormally expressed in bone-metastatic tumors, serves as a critical regulator of osteogenesis and metastasis in human malignancies including breast cancer." (PMID 41230330, 2025). "Evidence suggests that Runx2 is highly expressed in metastatic breast cancer cells and plays a significant role in regulating breast cancer progression." (PMID 41230330, 2025). "EXOs derived from adipose mesenchymal stem cells deliver miR-218 to breast cancer cells, where miR-218 can inhibit angiogenesis and EMT by targeting Runx2 and Rictor, preventing breast cancer progression." (PMID 40486870, 2025). "Specifically, in this study, we perform immunohistochemical and bioinformatic analyses to investigate the possible prognostic role of vimentin, SDF-1, BMP-2, BMP-4, PTX3, OPN, RANKL, and Runx2 on a large cohort of breast cancer patients." (PMID 39859358, 2025).
breast carcinoma (continued). "An important finding in thyroid and breast cancer samples is that the metastatic potential is correlated with co-expression of RUNX2 and SREBP1." (PMID 41511334, 2025). "Beyond osteogenesis, RUNX2 has been shown to foster tumor progression in osteosarcoma, gastric, pancreatic, and breast cancer, as well as promoting bone metastases." (PMID 40307935, 2025). "Runt-related transcription factor 2 (RUNX2) is a key driver of breast cancer bone metastasis; α5 integrin, as a critical RUNX2 target, augments the chemotactic and adhesive capabilities of breast cancer cells." (PMID 40894924, 2025). "In TNBC, RUNX2 leads to chemoresistance in breast cancer cells through transcriptional activation of the target gene, MMP1." (PMID 38430423, 2024). "Genes involved in the enrichment of the PI3K-Akt-mTOR pathway included Runx2 and Skp2, which are involved in mammary gland development and breast cancer." (PMID 38059614, 2024). "Runx2 requires co-activator core-binding factor beta (CBFb) to regulate gene expression in breast cancer cells." (PMID 38247829, 2024). "Inhibition of RUNX2 expression is a new perspective to prevent breast cancer invasion and metastasis." (PMID 38885076, 2024). "Mendoza-Villanueva and colleagues have shown that Runx2 and CBFb inhibit osteoblast differentiation in bone metastatic breast cancer cells and that this inhibition is mediated by the induction of sclerostin expression." (PMID 38247829, 2024). "It has been reported in the literature that RUNX2 is able to recruit the NuRD (MTA1)/CRL4B complex and accelerate breast cancer progression and bone metastasis and RUNX2 is also associated with breast cancer drug resistance." (PMID 38885076, 2024). "Runt-related transcription factor 2 (Runx2) is known to mediate activation of osteoclast activity and inhibition of osteoblast differentiation by metastatic breast cancer cells." (PMID 38247829, 2024). "The investigation encompassed human breast cancer T47D cells and prostate cancer C4-2B cells, highlighting the pivotal roles of AR, Runx2, and dihydrotestosterone (DHT) in this pathway." (PMID 37759471, 2023). "Breast cancer cells express four types of 5-HT receptors, and their binding to 5-HT induces PTHrP through RUNX2, inhibits osteoblast maturation and activates osteoclasts through the RANKL pathway." (PMID 37296983, 2023). "As expected, the expression of miR-218 is decreased and the expression of Runx2 is increased in breast cancer samples compared to normal samples." (PMID 37968694, 2023). "In breast cancer, RUNX2 has been described to regulate cell metabolism and promote tumor progression by altering the expression of glycolytic genes or mitochondrial respiration." (PMID 37754231, 2023). "Various studies revealed their relevance to breast cancer risk, where a polymorphism occurred in the FGFR2 intron 2 location and modulated the interaction of two transcription factors named Oct-1/Runx2 and C/EBPb." (PMID 37107577, 2023). "Conditional Runx2 KO mice revealed roles for Runx2 in regulation of epithelial cell fate in mammary gland development and breast cancer." (PMID 36766749, 2023). "The authors went on to demonstrate that there was an inverse correlation between ERα expression and expression of RUNX2 target genes in breast cancer biopsies." (PMID 36831308, 2023). "A follow-up study showed that CADD522 also inhibited mitochondrial oxidative phosphorylation by decreasing the oxygen consumption rate plus ATP production in human breast cancer cells in a RUNX2-independent manner." (PMID 36936386, 2023). "RUNX2 was shown to be highly upregulated in pancreatic cancer, breast cancer, lung cancer, thyroid cancer, and head and neck cancer." (PMID 37108164, 2023). "RUNX2 modulated cancer stemness in a breast cancer study: RUNX2 overexpression in MDA-MD-231 cells led to an increase in sphere volume in a spheroid-forming assay." (PMID 37108164, 2023).